HIF1A (hypoxia inducible factor 1 subunit alpha)
Diseases named in the same sentence as HIF1A in open-access papers (continued):
Sharing a sentence is not in itself a finding about the gene and the disease.
tumor (continued). "STAT3 can cooperate with HIF-1α to enhance carbonic anhydrase IX (CAIX) gene transcription, especially in hypoxic tumor microenvironments." (PMID 41596231, 2026). "Although copper accumulation triggers cuproptosis 31, tumor cells in hypoxic and copper-rich TME develop resistance to cuproptosis through copper binding to HIF-1α, which inhibits ubiquitin-mediated degradation of HIF-1α and amplifies hypoxia." (PMID 41355954, 2026). "HIF‐1α, functioning as a transcription factor that governs GLUT1 expression, enhances glucose uptake in tumor cells and promotes aerobic glycolysis when overexpressed, a mechanistic insight corroborated by our previous investigations." (PMID 41541658, 2026). "To further examine the influence of tumor hypoxia, we generated a hypoxia signature based on genes upregulated in PDAC compared with normal pancreatic tissue and regulated by hypoxia-inducible factor 1-alpha (HIF-1α)." (PMID 41554705, 2026). "USP28 inhibitors, such as FT206 and vismodegib, destabilize oncogenic substrates (e.g., c‐Myc, HIF1α) by blocking USP2's deubiquitinase activity, thereby suppressing tumor growth." (PMID 40855785, 2026). "Hypoxia is a critical feature of the tumour microenvironment in small cell lung cancer (SCLC) and contributes to malignant progression through hypoxia-inducible factor 1 alpha (HIF-1α)-mediated transcriptional programs." (PMID 41869444, 2026). "The resulting fatty acid influx amplifies HIF‐1α/CCL2 signaling, establishing a positive feedback loop that fuels tumor growth." (PMID 41160815, 2026). "This reduction in HIF-1α protein levels therefore decreases VEGF expression, which impairs angiogenesis, thus limiting the tumor’s ability to support growth and metastasis." (PMID 41614951, 2026). "The overexpression of hypoxia-inducible factor-1α (HIF-1α) suppresses STING signaling and modulates lipid metabolism in tumor cells, leading to abnormal lipid droplet (LD) accumulation." (PMID 42187457, 2026). "Downregulation of PTEN reduces apoptosis and enhances angiogenesis through the HIF-1α signaling pathway, while suppression of PDCD4 and SPRY1 further facilitates tumor cell proliferation, migration, and invasion." (PMID 41511367, 2026). "The increased lipid supply to tumor reactivates the FA/HIF‐1α/CCL2 axis in cancer cells, further accelerating tumor growth and CCL2 secretion." (PMID 41160815, 2026). "All three compounds also decreased the expression of HIF-1α and PDK3, indicating interference with hypoxia-driven metabolic adaptation, a process frequently exploited by tumor cells." (PMID 41614887, 2026). "It explores RNS sources in the TME, including autonomous synthesis by tumor cells and secretion by immune cells (e.g., TAMs, TANs), and their modulation of key signaling pathways (e.g., PI3 K/Akt, NF-κB, HIF-1α)." (PMID 41036604, 2025). "scRNA-seq revealed compartment-specific target localization: AKT1/ESR1 in tumor cells, SRC/IL6 in myeloid cells, and MTOR/HIF1A across stromal compartments." (PMID 40746726, 2025). "In contrast, good prognosis tumours exhibited significantly higher WWOX expression (log2fc = 1.17), resulting in a markedly increased WWOX/HIF1A ratio (log2fc = 1.86)." (PMID 41007296, 2025). "Fusobacterium nucleatum can promote tumor cell glycolysis by activating HIF-1α and inhibiting OXPHOS, thereby providing energy and biosynthetic precursors for rapid tumor cell proliferation." (PMID 40852612, 2025). "Recent evidence demonstrates ANL’s capacity to reshape the tumor immune microenvironment and enhance anti-PD-1 efficacy through modulation of the VEGFR2/AKT/HIF-1α axis and TFRC-CXCL14 signaling." (PMID 41383473, 2025). "For example, resveratrol and sulforaphane have shown efficacy in suppressing HIF-1α activity and reprogramming immune responses, thereby compromising CSC survival and reducing tumor persistence." (PMID 41323785, 2025).
tumor (continued). "Upregulation of HIF-1α and VEGF indicated hypoxia-driven angiogenic signalling, while Ki-67 suppression reflected sustained tumour growth inhibition." (PMID 41148833, 2025). "Hypoxia-inducible factor 1α (HIF-1α) stabilization in the adipose tissue microenvironment further amplifies VEGF expression and glycolytic enzyme activity, supporting tumor growth and vascularization." (PMID 41301707, 2025). "Another major role of HIF1α is the upregulation of the Vascular Endothelial Growth Factor Receptor (VEGFR), ultimately leading to the overexpression of VEGF in tumor cells." (PMID 40806669, 2025). "According to specific research, AP-1 and HIF-1α frequently cooperate to activate LDHA transcription and increase tumor cells’ ability to produce lactate." (PMID 40917751, 2025). "This study highlights the prognostic significance of HIF-1α, LOX and ITGA5 expression in the tumor microenvironment, particularly in the context of KRAS/NRAS/BRAF mutation status." (PMID 39857068, 2025). "Importantly, the VHL/HIF-1α signaling axis emerges as a critical regulatory target, which not only mediates glycolytic suppression but may also serve as a therapeutic strategy to curb tumor metastasis." (PMID 41008845, 2025). "VEGF activates MMP-9: Through pathways such as hypoxia-inducible factor (HIF-1α), VEGF increases the expression of MMP-9, particularly in the tumor microenvironment." (PMID 41255610, 2025). "On the other hand, it activates HIF-1α, which transcriptionally upregulates VEGF to promote tumor angiogenesis." (PMID 41162811, 2025). "In addition, we know that in tumor hypoxic zones, the transcription of hypoxia-inducible factor-1α (HIF-1α) may activate the transcription of numerous genes involved in glucose uptake, glycolysis, and oxygen consumption, and may promote cancer cell invasion and migration." (PMID 40558563, 2025). "In order to maintain survival and expansion, tumor cells significantly upregulate the expression of hypoxia-inducing factors (HIF), specifically HIF-1α and HIF-2α, which regulate the angiogenesis process in a complex manner." (PMID 39897552, 2025). "During hypoxia, hypoxia-inducible factor 1-alpha (HIF-1α), the main transcriptional regulator, is frequently overexpressed in tumors and promotes tumor cell growth and survival by controlling both glycolysis and angiogenesis." (PMID 41353169, 2025). "In addition, whether other metalloproteinases are also regulated by HIF-1α to mediate the immune escape of tumor cells from the killing by NK cells, and whether common metalloproteinases (MMP2, MMP9, and ADAM10) are also regulated by factors parallel to HIF-1α, still require further research." (PMID 40563539, 2025). "The antigen-presenting ability of DCs is notably compromised by the hypoxic condition within the tumor microenvironment (TME), mediated by the hypoxia-inducible factor 1-alpha (HIF-1α)." (PMID 40333202, 2025). "Additional molecular mediators, including GNG2, a tumor suppressor limiting brain metastasis and FSTL3, which promotes tumor progression via HIF1α-dependent pathways, have emerged as actionable biomarkers for metastatic control." (PMID 41403952, 2025). "By blocking NF-κB/HIF-1α-mediated EMT and ECM remodeling, MTD effectively suppresses VM formation in ESCC under hypoxic tumor microenvironment conditions." (PMID 41019994, 2025). "The demonstrates that the combination therapy reduced HIF-1α and VEGF levels in lung tumors, leading to the reduction of tumor hypoxia and subsequent inhibition of tumour growth." (PMID 40011266, 2025). "ROS-mediated signaling pathways, including hypoxia-inducible factor 1-alpha (HIF-1α) and vascular endothelial growth factor (VEGF), promote new blood vessel formation essential for tumor growth and metastasis." (PMID 40214466, 2025).
tumor (continued). "Chronic low concentrations of NO—in contrast to toxic doses—promote tumor survival, proliferation, migration, and resistance to treatment, including through activation of PI3K/Akt, MAPK/ERK, HIF-1α pathways and inhibition of apoptosis." (PMID 40649317, 2025). "Taken together, these findings indicate that CypD OE in cancer cells impedes the HIF1α-EMT pathway in vivo, resulting in effective suppression of metastasis while leaving growth of the primary tumor unaffected." (PMID 40701956, 2025). "For instance, metformin, a widely used treatment for diabetic patients, has been shown to inhibit the HIF-1α/PFKFB3/PFK1 pathway in HCC cells, thereby suppressing glycolysis and exerting anti-tumor effects." (PMID 39980550, 2025). "These abnormal changes promote the activation of the HIF-1α and VEGF/VEGFR signaling pathways, resulting in severe hypoxia within the tumor microenvironment, which in turn enhances tumor cell plasticity and the formation of vascular-like channels." (PMID 41019994, 2025). "MAO-A knockout inhibited HPV-16 E7-induced cellular oxidative stress and metastatic capacity in vitro, while in vivo it mitigated HPV-16 E7-dependent tumor growth and metastasis along with the expression of EMT protein markers and HIF1α." (PMID 39714760, 2025). "Hypoxia-induced circRNF13, mediated by HIF-1α and EIF4A3, promoted PDAC tumor progression and glycolysis, circRNF13 has the potential to be a prognostic biomarker and therapeutic target for PDAC." (PMID 40630951, 2025). "The main mechanism involves the activation of HIF-1α or oncogenes (such as RAS) by hypoxia or inflammatory factors (such as IL-6 and TNF-α) in the tumor microenvironment, leading to the secretion of VEGF, mainly VEGF-A." (PMID 40438141, 2025). "HIF-1α and HIF-2α become stabilized under hypoxic conditions, where they initiate a coordinated transcriptional program that enables tumor cells to survive in low-oxygen environments." (PMID 41450919, 2025). "This deacetylation enhances the transcriptional activity of HIF-1α, ultimately upregulating multiple glycolysis-related genes downstream of HIF-1α, thereby driving the Warburg effect and facilitating tumor growth in CRC." (PMID 40032849, 2025). "Lactate produced by cancer cells stabilizes extracellular signal-regulated kinases 1/2 (ERK1/2), signal transducer and activator of transcription (STAT) 3, and HIF-1α to induce ARG-1, thereby inhibiting the T-cell function and promoting tumor growth." (PMID 39925801, 2025). "It inhibits the stabilization of HIF-1α through the activation of AMP-activated protein kinase (AMPK), which results in reduced tumor growth and improved efficacy of chemotherapy." (PMID 40136686, 2025). "In tumor cells, HS induces the upregulation of HSP70 expression, which further promotes the post-translational modification of HIF-1α, exacerbating the malignant characteristics of tumor cells." (PMID 39744422, 2025). "The ability of propolis to simultaneously target the HIF-1α, NF-κB, and STAT3 pathways underscores its unique potential to dismantle the signaling network that sustains the hypoxic and pro-inflammatory tumor microenvironment." (PMID 41302515, 2025). "MYC, FOXA1, HIF1A, PAM50 and both ROR are determined at the gene expression level in RNA extracted from FFPE tumor tissue using the nCounter platform." (PMID 40997111, 2025). "HIF-1α binds directly to HRE in the promoter region of the PD-L1 gene, enhancing the transcriptional upregulation of the ligand in several tumor types such as lung, breast, renal, head and neck cancers." (PMID 40963621, 2025).
tumor (continued). "The expression of HIF‐1α and CEPT1 in GC tumour tissues was significantly greater than that in adjacent tissues." (PMID 40954549, 2025). "Primary cell cultures from the cancerous ccRCC tumor cells, RCC2 and RCC3, were derived based on the expression of carbonic anhydrase IX (CAIX), a downstream target of HIF1α and a clinically relevant marker of hypoxia." (PMID 41301058, 2025). "Under hypoxic conditions, HIF-1α directly induces MMP9 transcription, facilitating basement membrane degradation and tumour cell extravasation." (PMID 40806577, 2025). "It binds to the PAS-B domain of HIF-1α/2α and prevents their interaction with HIF-1β, thereby reducing the transcription of hypoxic response genes and inhibiting tumor growth and vascularization." (PMID 40650173, 2025). "Once in the bloodstream, cells release from hypoxic stress, leading to a reduction of HIF-1α levels and restoration of DSG2 expression, which promotes tumor cell clustering." (PMID 41381723, 2025). "Upon inhibition of HIF1α in NK cells, an increased infiltration was observed in VHL mutant 786-O RCC tumor spheroids." (PMID 40736709, 2025). "Under hypoxic conditions, HIF-1α inhibits FAO by suppressing acyl-CoA dehydrogenase, thereby promoting tumor survival." (PMID 41200171, 2025). "Further, while HIF1A acts as a tumor suppressor, HIF2A promotes oncogenic potential by driving tumor progression and metastasis through activation of hypoxia-sensitive signaling pathways and overexpression of HIF2A target genes." (PMID 40332447, 2025). "Hypoxia is a critical feature of the PanNET tumor microenvironment, influencing the expression of markers such as carbonic anhydrase 9 (CA9), which is induced by HIF-1α." (PMID 41458541, 2025). "Garcinia alleviates extrinsic microenvironmental suppression by reducing hypoxic stress through inhibition of HIF-1α and VEGF, enhancing immune cell infiltration, and augmenting anti-tumor immunity when combined with anti-PD-L1 treatment." (PMID 41050070, 2025). "The aberrant activation of HIF‐1α is mainly responsible for the overexpression of VEGFA and contributes to tumor progression." (PMID 40515512, 2025). "Hypoxia‐inducible factor (HIF)‐1α is regulated by the ubiquitin‐conjugating enzyme E2S (UBE2S) to enhance the growth, invasion, and metastasis of the tumor in ESCC." (PMID 41427004, 2025). "Increasing expression of HIF-1α sequentially results in an upregulation of proangiogenic factors such as VEGF and platelet-derived growth factor (PDGF), promoting tumour angiogenesis." (PMID 41281029, 2025). "Further studies show that IH can drive PD-L1 overexpression through the upregulation of HIF-1α; IH increases HIF-1α and PD-L1 in tumor cells, weakening cytotoxic T cells and increasing TAMs, thus accelerating tumor progression." (PMID 41194928, 2025). "Using IHC staining, the expression of HIF‐1α and VEGF‐A in MTCQ1 tumour sections was significantly suppressed by PX‐478." (PMID 39757131, 2025). "Meanwhile, the rapid proliferation of tumor cells and angiogenesis create a hypoxic TME, which activates HIF-1α." (PMID 41200171, 2025). "Consistent with previous findings in the cell‐line derived cancer model, TZP significantly reduced the expression of the target proteins in tumor tissues, confirming that TZP inhibited the HIF‐1α‐mediated glycolytic pathway in human tumor cells." (PMID 40125821, 2025). "Beyond HIF-1α-mediated regulation, CD73 levels in tumor cells are also influenced by Wnt and cyclic AMP (cAMP) signaling, as well as cytokine-driven pathways, highlighting its integration into multiple oncogenic signaling networks." (PMID 40229283, 2025). "HIF1a upregulates CD47 expression, allowing tumour cells to avoid phagocytosis by macrophages and contributes to resistance against immunotherapy." (PMID 40806577, 2025). "This has been shown by in vitro data in which the inhibition of HIF-1a changes the TME to hot, reactivating tumor-infiltrating lymphocytes and makes immunotherapy more effective." (PMID 41012682, 2025).
tumor (continued). "Lactate regulates MDSC activation through the GPR81/mTOR/HIF-1α/STAT3 pathway, and blocking lactate production in tumor cells restores anti-tumor T cell responses." (PMID 40650086, 2025). "Hypoxia enhances Treg infiltration and stability via HIF-1α-induced CCL28 expression, which recruits Tregs to the tumor site." (PMID 39981236, 2025). "Further, the expression levels of HIF-1α and PDGF were assessed in tumor tissues harvested from each treatment group." (PMID 40702566, 2025). "Taken together, the current data demonstrated that the inhibitors of HIF‐1α and microtubule displayed the therapeutic effects on the OSCC tumour model." (PMID 39757131, 2025). "Mechanistically, DBD downregulated the expression of HIF-1α and VEGF in tumor tissues, leading to reduced MVD, as quantified via CD31 immunohistochemistry." (PMID 41210868, 2025). "HIF-1α, a transcription factor upregulated under hypoxia, is overexpressed in advanced LSCC, contributing to tumor aggressiveness." (PMID 39412136, 2025). "HIF-1α and ALDOC were important in enhancing the malignant degree of tumor and reducing the sensitivity of L-OHP chemotherapy." (PMID 40535800, 2025). "Tumor-derived lactate, absorbed by macrophages through monocarboxylate transporters (MCT1–4), activates HIF-1α, which subsequently upregulates the expression of vascular endothelial growth factor (VEGF) and arginase-1 (Arg1)." (PMID 40433363, 2025). "Upon activation of its toll-like receptor (TLR) by a tumor antigen, DCs quickly switch to aerobic glycolysis with lactate production and FAS via the TRAF6-PI3K-Akt, mTOR, and HIF-1a signaling pathways." (PMID 39796781, 2025). "HIF1A plays a critical role in CCA, with elevated expression levels observed in tumor tissues relative to normal bile ducts." (PMID 41300430, 2025). "HIFs, particularly HIF-1α and HIF-2α, are transcriptional regulators that respond to low oxygen levels in the tumor microenvironment." (PMID 40901111, 2025). "•It exerts potent antitumor effects by inhibiting tumor cell proliferation, migration, and invasion through suppression of the VHL/HIF-1α/VEGF signaling pathway, while also inducing apoptosis and G2/M phase cell cycle arrest." (PMID 41030787, 2025). "In summary, the interplay between hypoxia (governed by HIF-1α) and chronic inflammation (driven by NF-κB and STAT3) creates a self-reinforcing network that fosters tumor malignancy." (PMID 41302515, 2025). "HIF-1α and HIF-2α are the most studied isoforms and play pivotal roles in tumor adaptation to hypoxia." (PMID 41048631, 2025). "In hypoxic tumor microenvironments, MDK expression is induced via HIF-1α, which further contributes to epithelial-to-mesenchymal transition (EMT) and metastatic behavior." (PMID 40500394, 2025). "For instance, the accumulation of HIF‐1α induced by hypoxia in the TME can influence tumor metabolism, proliferation, and migration, thereby promoting tumor progression through various pathways." (PMID 40959206, 2025). "Inflammatory cytokines such as IL-6 and TNF-α upregulate HIF-1α and KRAS signaling, further enhancing tumor aggressiveness and resistance to therapy." (PMID 40342817, 2025). "In oral squamous cell carcinoma, HIF-1α can activate GPX4 by inhibiting the transcription of PER1, thus mediating the tumor’s resistance to ferroptosis." (PMID 40709182, 2025). "The immunosuppressive tumor microenvironment (TME), characterized by hypoxia-induced HIF-1α activation, metabolic reprogramming, and M2 macrophage polarization, further facilitates CSC resilience and therapy resistance." (PMID 41035670, 2025). "HIF-1α increases the expression of genes such as SNAIL, SLUG, and TWIST, which are crucial for mesenchymal transition, and promotes angiogenesis and tumor adaptation to hypoxia." (PMID 40362280, 2025).